CD4 (CD4 molecule)
Diseases named in the same sentence as CD4 in open-access papers (continued):
Sharing a sentence is not in itself a finding about the gene and the disease.
infection (continued). "CD4 count is an important predictor of disease progression, opportunities infection, deaths, and to understand the time interval between initial HIV infection to the first diagnosis." (PMID 33945664, 2021). "In contrast, both B cells and DC mediated HIV-1 trans infection of memory and activated CD4+ T cells." (PMID 33688006, 2021). "Future work will be needed to dissect the specific requirements for CD4+ T cells after i.n. infection." (PMID 33508041, 2021). "A previous report was able to evidence an increase in the frequency of GATA3 CD4 T cells following infection with Trichuris suis, but, in agreement with our result, was not demonstrated after PRRSV infection." (PMID 34956200, 2021). "Nevertheless, from day 30 after infection onward, pMT-10 mice displayed an increase in the frequency and number of CD4+ T cells expressing CD69 and Ki-67." (PMID 34554927, 2021). "In contrast, CGRP-mediated effects are not mediated via T-cells recruitment (i.e., as we observed in normal mice), or direct inhibition of CD4+ T-cells infection with HIV-1 [that is one of the reported mechanisms mediating HIV-1 transmission in the vagina." (PMID 34956215, 2021). "The HIV-1 trans-infection is a common mechanism of virus infection of CD4+ T cells by APCs such as dendritic cells and macrophages." (PMID 34603287, 2021). "The CD300a receptor blocking also enhanced the conversion of CD4+ T effectors cells to their memory phenotypes i.e., CCR7high CD62Lhigh up to 1.6 and 1.9 fold after 14 and 21 days post-infection, respectively." (PMID 35116028, 2021). "This effector CD4+ T-cell subset is developed under inflammation and infection, being induced during antiviral response to promote virus clearance through cytotoxicity and cytokine-dependent mechanisms." (PMID 34956200, 2021). "Recovery from infection in both children and adults was characterised by the generation of CD8 TCM and CD4 TCM up to 9 weeks post infection." (PMID 34721408, 2021). "From baseline to day 42 after infection, old animals showed a significant decline in circulating CD4+ T cells (P = 0.0157) alongside a significant expansion of CD8+ T cell frequencies (P = 0.0081)." (PMID 34491910, 2021). "Meanwhile, at 72 h post infection, the activated CD4+ T cells were mostly in the fifth and sixth divisions, whereas METTL3-deficient CD4+ T cells were dominant in third and fourth divisions." (PMID 33637761, 2021). "Comparable to HBV-specific CD8+ T cells, the CD4+ T cell response in cHBV is more narrow as compared to acute clearing infection, demonstrated by decreased recognition of epitopes." (PMID 34066322, 2021). "In our study, we observed that vaginal epithelial cells did facilitate infection of sorted CD4+ T cell subsets enriched for co-receptors CCR5/CXCR4." (PMID 33816339, 2021). "It is therefore important to understand the characteristics that allow these transcriptional factors to either be co-expressed or show dominate expression to mediate CD4+ T-cell fate commitment in the context of infection." (PMID 32999454, 2021). "Regarding the adaptive immunity mediated by T cells, spike-specific memory CD4+ T cells are detected in most convalescent individuals after 6 months post-infection." (PMID 34671348, 2021). "The frequencies of specific CD4+ T-cells were comparable at three months after vaccination and infection, and the frequencies and also proportions of specific central memory CD4+ T-cells as a percentage of specific CD4+ T-cells were similarly comparable." (PMID 34960185, 2021). "The relative proportions of circulating CD4+ T cells decreased significantly 1.3 mo after infection, whereas the circulating CD8+ T cells increased, but both returned to near-physiological levels by 6.1 mo." (PMID 33533915, 2021). "Other investigators have demonstrated B cell knockout mice retaining a predominantly CD4 + Th1-like response to malarial antigens throughout a primary infection." (PMID 34666102, 2021).
infection (continued). "In the experimental model of T-cell exhaustion induced by infection with Lymphocytic Choriomeningitis Virus, exhausted CD4+ T cells are subjected to ongoing chronic STAT1 activation and a desensitization of IFN-γ pathway." (PMID 34061845, 2021). "The mean respective CD4+ T cell counts per μL were 380 ± 131, 343 ± 140, 305 ± 89, 296 ± 103, and 281 ± 62 at 90, 180, 360, 540, and 720 days post-infection in the RP group." (PMID 34367176, 2021). "With such a potent adaptive immune response, HIV-1 established infections in CD4+ T cells and macrophages have evolved mechanisms to evade CTL responses." (PMID 33897659, 2021). "Since early adequate CD4+ IR has been related to lower infection-related morbidity and lower overall mortality, we evaluated CD4+ IR probability in omidubicel recipients." (PMID 34312498, 2021). "Innate immune cells migrate to the site of infection where they detect the parasite, mainly via Toll-like receptors (TLRs), and secrete IL-12, to stimulate CD4+ and CD8+ T cells, and natural killer (NK) cells to produce IFN-γ." (PMID 35003067, 2021). "This led to a faster and stronger local CD4 T cell response post infection, consisting of multifunctional IFNγ/TNFα-producing Th1 T cells and IFNγ/TNFα/IL-17-producing Th17 T cells, and a faster recruitment of innate immune cells." (PMID 34925371, 2021). "The infection decreases the number of CD4+ T lymphocytes through different mechanisms, among which bystander cell apoptosis, infected cell viral death, and CD4+ T lymphocytes death through cytotoxic CD8+ T lymphocytes that recognize infected cells." (PMID 34008717, 2021). "The most classic example is human immunodeficiency viruses (HIV), which induces low levels of CD4+ T cells and eventually lead to fatal conditions including severe infections and malignant tumors." (PMID 35096654, 2021). "CD8+ and CD4+ T‐cell populations of mice infected with mutant virus started to expand already 2 weeks post‐infection (Fig EV5A and B)." (PMID 34605140, 2021). "Upon CD4+ T-cell depletion, the CD4DTR mice had significantly increased lung and brain fungal burden that resulted in lethal infection, indicating that CD4+ T-cells are important for control of the pulmonary infection and to prevent dissemination." (PMID 35186781, 2021). "Eight weeks after EcoHIV infection, single cell suspensions were made from the spleens and were analyzed expression of PD-1 on CD4+ T cells by flow cytometry." (PMID 33923025, 2021). "Depletion of CD4+ T cells prior to infection resulted in a transient reduction in OT-I frequency and number and a sustained impairment of OT-I cytokine production and degranulation." (PMID 33508041, 2021). "Decreased proliferation of CD4+ T cells results in less functional subsets and cytokine production and will weaken immune response against infections." (PMID 34440709, 2021). "Here we observed that animals receiving Hsp presented an increased frequency of CD4+LAP+ T cells (after 12 weeks of infection), which suggests the role of this T cell type in our model." (PMID 34248935, 2021). "Resting CD4+ T cells were treated with these reagents along with IP-10 for 1 h before infection and activation." (PMID 34447368, 2021). "FACS analysis of splenic T cells concerning the presence of CD69 showed that mice treated with anti-IL-2 mAb had increased numbers of CD4+CD69+ splenic T cells 21 days after initial infection." (PMID 34869064, 2021). "This MΦ activation can be put down to the release of IFNγ by CD4+ T cells and again, as in the infection with O. tsutsugamushi, demonstrates that the T cell-derived IFNγ-MΦ axis, although essential for protection, has pathological side effects." (PMID 34452021, 2021). "This suggests that the lung homing CD4+ T cells were compartmentalised specifically to the route of vaccination or infection." (PMID 33549390, 2021).
infection (continued). "These chemokines are crucial for the recruitment of macrophages, plasmacytoid DCs and CD4+ T cells to the site of infection, which preferentially are clustered below the cervical epithelium in a chemokine dependent manner." (PMID 34093520, 2021). "Although this action of HIV-1 PR is attributed to the reduction of CD4 T-cells during productive infection and in terminal disease, HIV-1 PR mediated apoptosis makes it deleterious for the virus to replicate." (PMID 33986734, 2021). "Using a C.t. transcervical (TC) infection model, CD4 Trm cells showed superior protection compared to systemic CD4 T cells." (PMID 34925371, 2021). "To test the ability of these AM- and plasma-derived Env proteins to allow infection of CD4+ T cells and MDMs, we cloned the env genes into an NL4-3 env deleted HIV backbone to generate replication-competent virus." (PMID 33594125, 2021). "The shift of relatively high affinity CD4 T cells toward a Tfh cell phenotype during Clone-13 infection is well documented." (PMID 33684030, 2021). "In the infection-naïve participants, the first vaccination dose primed a spike-specific CD4+ T cell response, which was further boosted with the second dose (top left)." (PMID 34636722, 2021). "In a mouse test to analyze infection caused by Candida albicans, reducing the expression of TLR2 lowers the quantity of CD4+CD25+ Treg cells and decreases the fungal burden." (PMID 34222495, 2021). "This seems paradoxical since depletion of CD4+ T cells during the chronic phase of infection results in reactivation." (PMID 34943793, 2021). "Treatment of mice with anti-CD4 antibodies, by i.n. and i.p. administration, significantly reduced the numbers of CD4 T cells in the nasal tissue during re-infection with B. pertussis." (PMID 33976385, 2021). "Once the infection is resolved, antigen-specific CD4+ and CD8+ effector T cells decline in number and a small population is usually maintained as antigen-specific memory CD4+ and CD8+ T cells." (PMID 33917629, 2021). "The generation of CD8 TCM and CD4 TCM cells up to 9 weeks post infection were common to both SARS-CoV-2-positive children and adults." (PMID 34721408, 2021). "Together these data indicated that CCHFV-infection of mice induces a robust polyfunctional CD4+ and CD8+ T-cell response." (PMID 33572859, 2021). "Neutrophilia and CD4+ T lymphopenia (including Treg cells) were observed during the acute phase of infection; increases in CD8+ cells were noted during the convalescent phase; and no changes in natural killer cells were noted." (PMID 34287349, 2021). "Here we reported and validated a newly designed dual fluorescent reporter virus, DFV-B, infection with which primary CD4+ T cells can directly label latently infected cells and generate a latency model that was highly physiological relevant." (PMID 33835029, 2021). "The frequencies of %CD29hi CD4+ T cells were reduced during the acute (P = 0.0469) and chronic (P = 0.0078) phases of untreated infection." (PMID 34721397, 2021). "To putatively recapitulate the early events in vaginal transmission of HIV we evaluated the transmission of sequestered virus to specific populations of CD4+T cells known to be permissive to infection." (PMID 33816339, 2021). "Compared with the plasma viral load, duration of infection showed a strong correlation with changes in CD4+ T cells in the blood." (PMID 34630335, 2021). "IL-17A was found to be upregulated in all S. epidermidis infected mice, with higher systemic IL-17A cell responses in mice that cleared the infection, which was found to be produced by CD4+ and γδ+ T cells in the bone marrow." (PMID 34240122, 2021). "Intriguingly, in certain infections such as influenza, unique populations of CD4 T cells can exhibit cytolytic capacity." (PMID 34910301, 2021).
infection (continued). "We infected wild-type C57BL/6J mice with LCMV Armstrong strain and observed elevated expression level of PDK1 in Tfh cells compared with naïve CD4+ T or Th1 cells on day 8 post-infection (8 dpi), which suggested potential roles of PDK1 in Tfh cells." (PMID 33595435, 2021). "(B) MDS plots of the phenotypes of spike-specific CD4+ T cells in infection-naïve and convalescent individuals after first and second dose vaccinations." (PMID 34636722, 2021). "When visualized as a dot plot, it was apparent that the spike-specific CD4+ T cells from infection-naïve individuals segregated away from those from the convalescents." (PMID 34636722, 2021). "Here, we characterized variants isolated from one of the original infected animals with CD4 depletion after nearly 4years of infection to identify determinants of increased replication fitness." (PMID 34867922, 2021). "Nevertheless, our data demonstrate, somewhat surprisingly, that levels of SARS-CoV-2-specific CD4+ T-cells and central memory CD4+ T-cells are comparable at three months following vaccination and infection." (PMID 34960185, 2021). "We have recently shown that prolonged treatment with antitubercular antibiotics induces apoptosis in activated CD4+ T cells and this phenomenon renders animals hypersensitive to TB re-activation and re-infection." (PMID 34415976, 2021). "Similar to in submucosal DCs and macrophages, infection by HIV-1-P90A was restored upon depletion of huTRIM5α in primary human CD4+ T cells or in Jurkat cells." (PMID 33669846, 2021). "There is evidence for astrocytes to harbor productive infection of HIV through direct contact with CD4+ infected T lymphocytes, although at low levels of detectability." (PMID 34451992, 2021). "With DFV-B infection, we can sort out latently infected primary CD4+ T cells, in which more than 50% can be reactivated by subsequent PMA and ionomycin stimulation." (PMID 33835029, 2021). "Despite these study limitations, our observations are still consistent with data that SARS-CoV-2–specific CD4+ T cell responses are more prominent than CD8+ T cell responses after infection and vaccination." (PMID 34591596, 2021). "CD4+TNF-α+T cells were significantly higher in the low dose group than the high dose group at week 1 post-infection." (PMID 34484203, 2021). "Specific CD4+ T cell fluctuate in parallel with HAV viremia until the resolution of infection, suggesting a predominant role of the CD4 population in viral clearance." (PMID 33430234, 2021). "As expected and consistent with the proviral role of IL-17RA signaling, MHV68 infection triggered an increase in MHV68-specific CD4 T cell population expressing IL-17A following ex vivo restimulation with immunodominant MHV68 epitopes." (PMID 33824206, 2021). "CD4+ T cells increase significantly after primary infection and secrete a variety of cytokines that regulate cellular and humoral immunity." (PMID 35062693, 2021). "Further infections using primary memory CD4+ T cells and different HIV-1 strains, including transmitted founder viruses, confirmed these observations." (PMID 34154423, 2021). "As a result, during untreated infection, most proviruses are eliminated along with the short-lived effector CD4+ T-cells that harbor them, with relatively few such cells transitioning back to long-lived memory cells." (PMID 34489909, 2021). "Th17 cells continued to increase from 2.3% of CD4+ T cells at baseline to 16.5% at 4 weeks post-infection." (PMID 33959105, 2021). "IL-17 production by activated CD4+ T cells and CD4+ Trm significantly increased during infection with WT." (PMID 34564636, 2021). "Due to the inflammatory environment, these fibroblasts will have low levels of cell-surface HA, further increasing their ability to efficiently promote infection of the infiltrating CD4+ T cells." (PMID 33976386, 2021).
infection (continued). "Our results establish the association between infection, T-cell homeostasis, and expression of PD-1 and TIGIT in long-lived CD4 T-cell subsets prior to ART with CD4 T-cell recovery and HIV persistence on-ART." (PMID 34449812, 2021). "The frequency and absolute number of early-stage TFH cells of Ddb1-TaKO SMARTA CD4+ T cells were similar to that of WT counterparts at day 3 after LCMV Armstrong infection." (PMID 34526995, 2021). "In contrast, the resistant strain SV/129 mice upregulate IL-10 expression after infection in CD4+ T cells only 8 weeks post-infection." (PMID 33680991, 2021). "In summary, our study designed and put forward a new dual fluorescent reporter virus, DFV-B, infection of which can directly mark latently infected primary CD4+ T cells." (PMID 33835029, 2021). "Combined, these data show that CD4 T-cells are important for controlling lung fungal burden, are involved in preventing systemic dissemination and ultimately mortality during UgCl223 infection." (PMID 35186781, 2021). "For the cut-offs defined here, more than 90% of subjects with verified infection had CD4+ reactivity to SARS-CoV-2 peptide pools S1 and/or SMN at TP4." (PMID 34795668, 2021). "HLA-II polymorphisms dictate the repertoire of peptides presented for CD4+ T cell recognition and shape the response elicited, which can influence the outcome of infection or vaccination." (PMID 34004174, 2021). "Instead, infection with V. cholerae primed Th1 and Th17 responses, with a shift toward Th1 to Th2 CD4+ T-cell responses." (PMID 34732259, 2021). "Teasing apart these two possibilities will require detailed understanding of the micro‐location of memory CD4 T cells within peripheral and lymphoid organs and which antigen‐presenting cells reactivate memory CD4 T cells following immunisation and infection." (PMID 32931017, 2021). "Since all pigs in that study were both vaccinated and infected it remained unclear to what extent the vaccination influenced the CD4+ T-cell response measured after STM challenge infection." (PMID 34451970, 2021). "Within the LP, parasite specific CD4+ T cells were strongly induced by infection in both WT and KO mice." (PMID 34597344, 2021). "In the periphery, upon antigen presentation by DCs, naïve CD4 T cells become activated and differentiate into specialised subsets of T cells which migrate to sites of pathogen exposure to clear infection." (PMID 33872331, 2021). "Iron loading prior to infection fostered bacterial burden and, unexpectedly, reduced differentiation of CD4+ T helper cells type 1 (Th1) and expression of interferon-gamma (IFNγ), a key cytokine to control infections with intracellular pathogens." (PMID 34108960, 2021). "Upon infection, human T-cells rapidly increased in the blood and lymphoid tissues, particularly CD4+CD25+ T-cells." (PMID 34685494, 2021). "(A) The frequency of spike-specific CD4+ T cells is similar in infection-naïve and convalescent individuals two weeks after the second vaccination dose." (PMID 34636722, 2021). "We observed that by day 7 post-infection, the percentage of CD4+ T-cells, CD8+ T-cells, γδ T-cells and B-cells in PBMC decreased in BTV-8 infected sheep when compared to mock infected counterparts." (PMID 34452376, 2021). "After 12 months on ART (24-months post-infection), CD4 counts in ART chronically treated individuals remained significantly lower compared to HIV uninfected participants (p=0.001) and the ART hyperacute treated group at 12-months (p=0.008)." (PMID 34630420, 2021). "Simultaneously, we found that compared with noninfected mice, the CD25+ Tregs (p < 0.05) and CD25+Foxp3+ Tregs (p < 0.001) in CD4+ T cells of the spleen of mice treated with A. fumigatus increased significantly within 72 h after infection." (PMID 34222495, 2021). "Taken together, these results support that B lymphocytes have a unique ability to mediate highly productive trans infection of naive CD4+ T cells with R5-tropic HIV-1." (PMID 33688006, 2021).